AR (androgen receptor)
Diseases named in the same sentence as AR in open-access papers (continued):
Sharing a sentence is not in itself a finding about the gene and the disease.
prostate carcinoma (continued). "Androgen/androgen receptor (AR) signaling plays pivotal roles in the prostate development and homeostasis as well as in the progression of prostate cancer (PCa)." (PMID 25943311, 2015). "Modest overexpression of AR in prostate cancer cells was sufficient to promote the castrate resistant growth of xenograft tumors." (PMID 25950519, 2015). "The androgen receptor drives prostate cancer (PCa) development and progression to lethal metastatic castration-resistant disease." (PMID 26452038, 2015). "Our study shows that androgen independence can be achieved through the inhibition of specific genes and reveals a novel set of genes that regulate AR signaling in prostate cancers." (PMID 26036626, 2015). "Predictably, AR-independent prostate cancer is highly heterogeneous, but a major established subtype is neuroendocrine prostate cancer (NEPC)." (PMID 25896606, 2015). "Using an unbiased approach, we have now identified the AR, the major driver of prostate cancer, as a downstream mediator of AMPK signalling in prostate cancer cells, adding an important new dimension to the role of AMPK in this cancer type." (PMID 25003216, 2014). "Although androgen receptor (AR) pathway is crucial for prostate cancer growth and progression, evidence supporting a favorable risk-benefit ratio of androgen deprivation therapy (ADT) is currently limited to high-risk PCa or metastatic disease." (PMID 24744780, 2014). "We demonstrated that SPOP promotes AR degradation and inhibits the transcriptional activity of the AR and AR-mediated prostate cancer proliferation." (PMID 24508459, 2014). "In contrast, enzalutamide has been reported to impair liganded AR nuclear entry in prostate cancer cells, as we see in this study in breast cancer cell lines in culture and xenografts." (PMID 24451109, 2014). "Heat shock protein 90 (Hsp90) is a molecular chaperone, which regulates the activation, maturation and stability of critical signaling proteins involved in prostate cancer, including the AR." (PMID 25072314, 2014). "Standard therapy of disseminated prostate cancer in hormone-naive patients is based on androgen-deprivation therapy or androgen receptor antagonists." (PMID 25243154, 2014). "Of note, AR protein was also significantly downregulated in LNCaP-abl cells, which represent a castration-resistant prostate cancer phenotype." (PMID 24484909, 2014). "Prostate cancer cell addiction to the androgen receptor (AR) forms the basis both for initial androgen deprivation therapy as well as the new second-generation androgen ablative agents (abiraterone and enzalutamide)." (PMID 24249419, 2014). "Two recently approved therapies for advanced prostate cancer directly target the androgen receptor signaling pathway: abiraterone by preventing androgen synthesis, and enzalutamide by blocking interaction of the receptor with its ligands." (PMID 25424879, 2014). "Berberine suppresses AR, which is known to be activated in cancer signaling and suggests that Berberine presents a promising agent for the prevention and/or treatment of prostate cancer." (PMID 24397863, 2014). "In-depth studies are needed to accurately determine the activation and inactivation of specific signaling pathways during development of insensitivities of prostate cancer cells to AR antagonistic drugs." (PMID 24387052, 2014). "AZD3514 inhibits and down regulates the androgen receptor (AR) and has undergone clinical trials in prostate cancer." (PMID 24674711, 2014). "Prostate cancer generally responds poorly to standard chemotherapy, but is heavily dependent on signaling of the androgen receptor (AR) for growth and survival." (PMID 24562461, 2014). "Prostate cancer growth is dependent upon the Androgen Receptor (AR) pathway, hence therapies for this disease often target this signalling axis." (PMID 24659630, 2014). "Here we show for the first time that the bone microenvironment itself altered AR function and rendered prostate cancer castrate resistant." (PMID 25278011, 2014).
prostate carcinoma (continued). "Due to the important role of ARs in sustaining prostate cancer progression, second line hormone therapy is frequently employed in prostate cancer to target persistent AR activation." (PMID 25494980, 2014). "We have also demonstrated that bromodomain inhibitors such as JQ1 are more efficacious than direct AR antagonism in treatment of castration-resistant prostate cancer in mouse models." (PMID 25928204, 2014). "On another front in prostate cancer control it is well known that the androgen receptor has been a target for prostate cancer for a long time." (PMID 24598693, 2014). "Since the androgen receptor is a driver of prostate cancer, we included both conditions where possible." (PMID 24497837, 2014). "As a consequence, through enhanced acetylation of the chaperone HSP90 and subsequent dissociation and degradation of the AR, AR-mediated signaling was inhibited in prostate cancer cells." (PMID 25322458, 2014). "Prostate cancer is driven by androgen receptor signaling, and is likely also influenced by basic cellular processes that contribute to other cancers." (PMID 24497837, 2014). "For example, multiple deubiquitinating enzymes have been identified which influence AR signaling in both cytoplasm and nucleus including TRIM68 which is specifically upregulated in prostate cancer and influences AR stability." (PMID 24922532, 2014). "Growth assays demonstrated that these repressive effects upon the AR do translate to growth inhibition of prostate cancer cells." (PMID 24659630, 2014). "Bicalutamide had little effect on reducing tumor burden in the bone yet still decreased tumor PSA expression and increased AR expression, thus, this model closely recapitulated castrate-resistant, human prostate cancer bone metastatic disease." (PMID 25278011, 2014). "We found that depleting Usp12 protein resulted in the sensitisation of prostate cancer cells to Akt inhibition irrespectively of their androgen sensitivity and AR status." (PMID 25216524, 2014). "A recent whole-genome, RNAi-based screen identified Med19 as an important element of Androgen Receptor activity in prostate cancer cells where gene expression levels also correlated with clinical outcome." (PMID 24786462, 2014). "AR signaling is essential for the growth and survival of prostate cancer (PCa), including most of the lethal castration-resistant PCa (CRPC)." (PMID 25333263, 2014). "For example, overexpression of the full-length AR (AR-FL) was shown to convert prostate cancer growth from a castration-sensitive to a castration-resistant stage." (PMID 24722067, 2014). "The androgen receptor (AR) plays a key role in both normal prostate biology and prostate cancer progression and, as a result, targeting of AR signalling is a major therapeutic strategy for advanced prostate cancer." (PMID 25003216, 2014). "Knockdown of endogenous SPOP by two independent SPOP-specific small interfering RNAs (siRNAs) increased AR protein levels in both LNCaP and C4-2 prostate cancer cells." (PMID 24508459, 2014). "The AR is a ligand activated transcription factor, which plays a central role in prostate cancer development and progression, with androgen deprivation therapy being the standard treatment for prostate cancer 139,140." (PMID 24629090, 2014). "PARM1 is part of the Golgi apparatus that is androgen-responsive, and researches demonstrate that the Golgi apparatus embody new mechanisms of the androgen receptor (AR)-mediated signaling and they are useful biomarkers for prostate cancer diagnosis/prognosis." (PMID 25151146, 2014). "ERBB2 and ERBB3 considerably increase the androgen-dependent AR transactivation of reporter genes in prostate cancer cells." (PMID 24739220, 2014). "Niphatenone B binds covalently to the AF-1 region of the AR NTD and blocks the proliferation of prostate cancer cells that are dependent on functional AR." (PMID 25268119, 2014).
prostate carcinoma (continued). "Androgen supplementation significantly reduced secretion and activity of MMP-9 in AR-positive prostate cancer cells grown in androgen-depleted media." (PMID 24978435, 2014). "The androgen receptor (AR) has been a target for prostate cancer for a longtime, however, there are limitations as to why anti-androgens are only effective for a short period of time." (PMID 24598693, 2014). "In summary, we have been unable to show a convincing role for PCGEM1 or PRNCR1 in aggressive prostate cancer or AR signaling." (PMID 24727738, 2014). "This evidence shows a direct role for AhR in androgen receptor dependent growth of prostate cancer cells." (PMID 24755659, 2014). "In about 30% of prostate cancers, the androgen receptor is genomically amplified, which enables these cancers to become resistant to androgen deprivation therapy with the drugs leuprolide and bicalutamide." (PMID 25198391, 2014). "Such AR NTD inhibitors would be of clinical value for the treatments of diseases of the androgen axis such as prostate cancer." (PMID 25268119, 2014). "Most patients inevitably fail this therapy, progressing to castration-recurrent prostate cancer (CR-CaP) typically presenting as bone or lymph node metastases whose growth depends on sustained androgen receptor (AR) signaling." (PMID 24983969, 2014). "Finding novel compounds that have unique molecular mechanisms of action to block the AR is of high interest for the treatment of advanced prostate cancer." (PMID 25268119, 2014). "Herein, the CAMK2N1 was shown to contribute to the human prostate cancer cell growth and survival through AR-dependent signaling." (PMID 25296973, 2014). "Defining factors that influence the sensitivity of prostate cancers to therapeutics targeting the AR-axis is critical for predicting treatment efficacy and identifying resistance mechanisms to prioritize future research efforts." (PMID 25356728, 2014). "We observed a dose dependent decrease in expression of AR in prostate cancer cells with concentrations as low as 40 μg/ml and 20 μg/ml in 22Rv1 cells and LNCaP cells, respectively." (PMID 24598693, 2014). "Further, two lncRNAs termed PRNBR1 and PCGEM1 that are upregulated in aggressive prostate cancer, synergistically and coordinately bind the carboxyterminal part of the androgen receptor (AR) and are required for AR-dependent gene transcription." (PMID 24723937, 2014). "AR regulates genes involved in proliferation and survival of prostate cancer cells and is a validated drug target for all stages of prostate cancer." (PMID 25268119, 2014). "Immunogenic modulation by ADT was dependent upon AR expression, since improved tumor-cell sensitivity to T cells was only seen in AR+ prostate cancer cells." (PMID 25344864, 2014). "Knocking down AR-FL or AR-Vs by shRNA in xenograft models can delay the progression of prostate cancer to castration resistance and/or suppress the growth of prostate tumor that has already progressed to the castration-resistant state." (PMID 25375370, 2014). "AR antagonist Casodex, a pharmaceutical drug commonly is used as an anti-androgen therapy to treat recurrent prostate cancer." (PMID 25296973, 2014). "The androgen receptor (AR) plays a central role in the oncogenesis of different tumors, as is the case in prostate cancer." (PMID 24779793, 2014). "In summary, these results showed that deregulation of the cell cycle by inhibition of the activity of the upstream signaling molecules Cdk1 and Cdk2 is at least partly involved in NED modulation in AR-positive prostate cancer cell lines LNCaP and LAPC-4." (PMID 24884804, 2014). "A number of androgen receptor (AR) transcriptional co-regulators have been identified to play important roles in prostate cancer (PCa)." (PMID 25150365, 2014). "The androgen receptor (AR) is a ligand activated steroid hormone receptor that plays a vital and significant role in developing the function of normal prostrate as well as in prostate cancer development and progression." (PMID 25295272, 2014).
prostate carcinoma (continued). "In contrast, another study indicated ERG can bind to AR and suppress AR expression in prostate cancer VCaP cells." (PMID 24739220, 2014). "Using this approach we were able to identify and validate the AR as a novel downstream mediator of AMPK signalling in prostate cancer cells." (PMID 25003216, 2014). "To demonstrate that AR + TNBC cell lines are responsive ligands, we measured the proliferation of the AR-dependent prostate cancer cell line LNCAP and AR + TNBC cell lines five days after treatment with increasing doses of Dihydrotestosterone (DHT)." (PMID 25103565, 2014). "Some of the crucial proteins affected by AS in prostate cancer [e.g., the androgen receptor (AR), zinc finger transcription factor Kruppel-like factor 6, Bcl-x, and cyclin D1] are known to contain IDPRs." (PMID 25988147, 2014). "Taken together, our results suggest modified MID1 expression in prostate cancer along with high AR expression levels, reflecting one mechanism that contributes to prostate cancer progression." (PMID 24913494, 2014). "Androgens stimulate prostate cancer cell growth via the Erk-2 pathway, where Erk-2 activation increases the androgen receptor complex content in the prostate cells." (PMID 25533015, 2014). "We provide molecular characterization of the AR signaling pathway in circulating prostate cancer cells." (PMID 25424879, 2014). "In contrast, calpain 1 expression was relatively stable in both AR-positive and AR-negative prostate cancer cells." (PMID 24297527, 2014). "As AR is the pivotal molecular driver of prostate cancer evolution and progression and is the foremost therapeutic target for mCRPC, our current study focused on AR interrogation." (PMID 25424879, 2014). "Taken together, these results suggested a functional interaction between CAMK2N1 and AR during prostate cancer progression." (PMID 25296973, 2014). "The action of androgens is predominantly mediated through AR and its co-activators, which have been shown to be critical regulators of the G1 to S transition in prostate cancer cells." (PMID 24884804, 2014). "We propose that shikonin, an anticancer drug extracted from natural sources, induces inhibition of cell growth through modulation of AR in androgen-responsive prostate cancer cells and is a candidate for use in cancer chemotherapy for human prostate cancer." (PMID 24573652, 2014). "The constituent has a potential therapeutic effect on prostate cancer cells through the downregulation of AR and AR-related cofactors AP-1, NF, and CBP." (PMID 25295272, 2014). "Of note, the PI3K pathway is the key node for the signal transmission of the stimuli from membrane RTKs in relation to the control of the AR in prostate cancer." (PMID 24779793, 2014). "The androgen-androgen receptor (AR) signaling pathway is essential for the development and progression of prostate cancer and is a key target of many therapeutic agents." (PMID 25084170, 2014). "These lncRNAs also promoted ligand-independent activation of the AR transcriptional program, thereby potentially contributing to castration-resistant prostate cancer development." (PMID 25473436, 2014). "Reduced expression of CAMK2N1 was correlated to recurrence-free survival of prostate cancer patients with high levels of AR expression in their tumor." (PMID 25296973, 2014). "To investigate the role of CAMK2N1 in inhibiting AR-positive prostate cancer growth in vivo, we established C4-2 cells stably transduced with lentiviral shRNAs targeting CAMK2N1." (PMID 25296973, 2014). "In prostate cancer FOXA1 has been found to be a pioneer factor for AR for some binding events, but also a repressor." (PMID 24849812, 2014). "Androgen deprivation and other methods to disrupt androgen receptor (AR) signaling were the first targeted cancer therapy and have been the mainstay of prostate cancer therapy for more than seven decades." (PMID 25424879, 2014).
prostate carcinoma (continued). "Together, these findings suggest that SPOP promotes AR protein ubiquitination and proteasome degradation and inhibits prostate cancer cell growth in an AR-dependent manner." (PMID 24508459, 2014). "Taken together, our data suggest that AR signaling can promote prostate cancer through the upregulation of G6PD and therefore, the flux of sugars through the pentose phosphate pathway." (PMID 24861463, 2014). "IL-8 increases transcriptional activity of the AR and facilitates transition to androgen independence and bicalutamide resistance of prostate cancer." (PMID 25248616, 2014). "Within the last three years two alternative anti-androgen strategies reached clinical application offering new options in both pre- and post-chemotherapy setting which emphasises the androgen receptor as sustained therapy target in prostate cancer." (PMID 25332874, 2014). "In this study we analyzed the effects of the stilbene RSV and the synthetic fluorinated dialkylaminostilbene ((E)-4-(2, 6-Difluorostyryl)-N, N-dimethylaniline or FIDAS-3 on AR- and ARΔLBD in prostate cancer cells in vitro and in vivo." (PMID 24887556, 2014). "Androgen deprivation therapy, which disrupts androgen receptor (AR) signaling through castration or AR antagonists, is the first-line treatment for disseminated prostate cancer." (PMID 25375370, 2014). "Metformin disrupts the MID1 protein complex and reduces AR protein levels in prostate cancer cells identifying AR as an indirect metformin target." (PMID 24484909, 2014). "Intriguingly, recent studies have unveiled a high degree of crosstalk between AR signalling and metabolic pathways in prostate cancer cells." (PMID 25003216, 2014). "The ubiquitin ligase MID1, which is over-expressed in prostate cancer tissue in a stage-dependent manner, enhances androgen receptor protein levels." (PMID 24913494, 2014). "Androgen receptor is a primary transcription factor involved in the proliferation of prostate cancer cells." (PMID 25285958, 2014). "Similar to the central role which the AR plays in prostate cancer, the estrogen receptor (ER) is seen as a key player in breast cancer." (PMID 25594026, 2014). "The two most frequent aberrantly activated signaling pathways found in prostate cancer are controlled by the AR and PI3K." (PMID 24913494, 2014). "NWD1 knockdown potently suppressed growth of androgen-dependent LNCaP prostate cancer cells, thus showing its functional importance in an AR-dependent tumor cell model." (PMID 24681825, 2014). "Our objectives for this study are to determine the effects of cisplatin on prostate cancer cell growth, the AR and PSA expression, as well as the regulatory mechanisms of cisplatin on the gene expression of BTG2 in prostate cancer cells." (PMID 24981574, 2014). "Previous microarray data performed by our group showed MID1 to be negatively regulated by androgens in various AR positive prostate cancer cell lines (unpublished data)." (PMID 24913494, 2014). "This flexibility and specificity allowed an integrated evaluation of AR within CTCs in patients with metastatic castration-resistant prostate cancer (mCRPC)." (PMID 25424879, 2014). "Increased expression of AR was reported for a vast majority of prostate cancer tissue samples, achieved through mechanisms such as AR gene amplification, which was found approximately in one third of patient samples, or post-transcriptional regulation." (PMID 24913494, 2014). "CAMK2N1 expression was inversely correlated with AR levels in prostate cancer, and patients with higher CAMK2N1 expression in their tumor have improved recurrence-free survival." (PMID 25296973, 2014). "AR, a ligand-activated transcription factor belonging to the steroid receptor super-family, is critically involved in prostate cancer progression as well as maintenance of the male reproductive organ." (PMID 24573652, 2014). "Prostate cancer cells expressing high levels of NEAT1 were recalcitrant to androgen or AR antagonists." (PMID 25415230, 2014).